AFP (alpha fetoprotein)
Diseases named in the same sentence as AFP in open-access papers (continued):
Sharing a sentence is not in itself a finding about the gene and the disease.
tumor (continued). "Notwithstanding its low sensitivity and accuracy AFP is still the most widely used tumour marker for HCC surveillance and diagnosis but there is the need for discovery of better tumour markers." (PMID 26341083, 2015). "Up-regulation of CCAT1 is correlated with tumor size, microvascular invasion, AFP and poor prognosis." (PMID 25884472, 2015). "A positive correlation between AFP serum levels and the stage of the tumor was shown in many studies." (PMID 26122937, 2015). "low frequency of smoking history, more frequent HBV, less frequent HCV, higher AFP levels, well-preserved liver function, larger tumor size, more advanced stage, more frequent application of surgical resection and chemotherapy as initial treatment." (PMID 26093092, 2015). "Hepatitis B virus (HBV)-X protein(HBx) is a transactivator of host several cellular genes including alpha-fetoprotein(AFP) and AFP receptor(AFPR) which contributes to HBV-associated tumor development." (PMID 25943101, 2015). "The most widely used tumor marker, serum alpha-fetoprotein (AFP), has contributed to a reduction in HCC mortality." (PMID 26114756, 2015). "Another example of this tumor type included mononuclear tumor cells that stained strongly positive for alpha-fetoprotein and weakly positive for anticytokeratin (CAM 5.2)." (PMID 25928039, 2015). "Although local resection was performed 2 months before the diagnosis of AFP tumor, the serum AFP level was normal." (PMID 25962419, 2015). "LRG1, as well as tumor size, serum AFP level, tumor multiplicity, clinical stage, vascular invasion, and tumor differentiation were shown to be responsible for the outcome of overall survival in both training cohort and validation cohort." (PMID 26517349, 2015). "More interestingly, the expression of IGF2BP1 was positively correlated with the level of AFP, the most widely recognized tumor marker for HCC." (PMID 26547929, 2015). "AFP serves as a tumor marker, as an indicator for treatment response, and as a follow up marker to detect early relapses." (PMID 25690034, 2015). "AFP has been reported to be a useful tumor marker for the detection of recurrence, and a predictive factor for patient survival after locoregional or systemic treatment in HCC." (PMID 26681337, 2015). "Thirty-five patients (12.4%) were classified as the young age group and showed larger tumor size (>5cm), higher Edmondson grade, more frequent intrahepatic metastasis and higher alpha-fetoprotein level (>200ng/mL) than old age group." (PMID 26093092, 2015). "Specifically, we showed that over-expression of ATAD2 correlated significantly with high AFP levels, advance tumor stages, and vascular invasion." (PMID 26497681, 2015). "Serum tumor markers including alpha-fetoprotein (AFP), carcinoembryonic antigen (CEA), and carbohydrate antigen 19-9 (CA 19-9) were within normal limits." (PMID 26546053, 2015). "Postoperatively, serum tumor makers were increasing: AFP, HCG, and LDH, respectively, from 5,2 μg/L, 2,9 UI/L, and 440 UI/L to 9,3 μg/L, 14,8 UI/L, and 486 UI/L." (PMID 26000192, 2015). "Further immunohistopathological examination revealed that the tumor was an AFP-producing adenocarcinoma of the rectum." (PMID 25962419, 2015). "The uptake of AFP by multiple cell types, including epithelial cells, activated lymphocytes and tumor cells, has been observed, although a specific cell surface receptor has not yet been definitively identified." (PMID 26199728, 2015). "AFP levels are associated with tumor size, and only about two-thirds of HCC patients with tumors <3 cm will have elevated AFP levels." (PMID 28943622, 2015). "Much different from the association between intratumoral Cbl and clinical parameters, the expression of peritumoral Cbl was significantly low in HCC patients with large tumor, high AFP level, microvascular invasion and HBeAg positive." (PMID 26474280, 2015).
tumor (continued). "Alpha-fetoprotein and Des-gamma-carboxyprothrombin are the most widely used tumour markers but their usefulness in different ethnic groups is still an issue of contention." (PMID 26341083, 2015). "Tumor markers, such as CA 125, CA 19-9, and alpha-fetoprotein, have limited use in the evaluation of pelvic masses since they are physiologically elevated during pregnancy." (PMID 25960900, 2015). "In univariate analysis, predictors of OS include ECOG performance status, concurrent VI and Mets, tumor size, serum AFP, bilirubin, albumin, AST levels, reasons for discontinuation of sorafenib, and PD within 4 months." (PMID 25860213, 2015). "On univariate analysis, age, Child-Pugh classification, tumor size, albumin, bilirubin, radiation dose, and AFP normalization were identified as significant parameters of OS." (PMID 26681337, 2015). "HB usually expresses α-fetoprotein (AFP), which is also elevated in the serum of 90% of children with this tumor." (PMID 25690034, 2015). "Microscopically, the tumor was composed of small arborizing vessels proliferating in the myxoid background, and the tumor cells were positive for AFP by immunohistochemistry." (PMID 26337640, 2015). "Among the independent predictors of MHCAT, the criteria for LT primarily represent tumour morphological characteristics, whereas AFP reflects the tumour biological activity at some level." (PMID 26096817, 2015). "After multivariate Cox regression analysis of these variables using AIC as a stopping rule, we identified eight risk factors as independent predictors for OS in HCC: tumor size, tumor capsule, pathological grades, TBIL, ALB, PT, AFP, and tumor number." (PMID 25776856, 2015). "Serum AFP concentration and tumor size were significant factors for the primary cohort, but not for the validation cohort." (PMID 25576919, 2015). "Univariate analysis showed that besides the inflammation-based prognostic scores, the presence of GGT, AFP, maximal tumor diameter, and vascular invasion were significant predictors of OS and DFS." (PMID 26356714, 2015). "It has been demonstrated that AFP promotes tumor progression, affects cell differentiation, growth regulation, tumorigenesis and is involved in pleiotropic activities." (PMID 25822740, 2015). "It is due to a heterozygous deletion on chromosome 19 that encodes a functional chimeric protein (DNAJB1-PRKACA) and characterized by being less aggressive with a normal alpha-fetoprotein (AFP) tumour marker and a female predominance." (PMID 26342351, 2015). "Serum AFP levels were significantly elevated (40 ± 9 ng/ml) in 63 % of MDR2−/− mice, with little correlation between serum AFP levels and tumor burden (R2 = 0.17, n = 10)." (PMID 25981587, 2015). "It is well known that clinico-pathological features, including AFP level, BCLC stage, tumor number, PVTT and metastasis, are risk factors associated with HCC survival." (PMID 26506519, 2015). "In week 23, MRI scans showed that the tumor mass had completely disappeared, and the AFP level had decreased to a normal level." (PMID 25649133, 2015). "Tumor growth was monitored by AFP detection in the serum as a surrogate marker of relative tumor burden and response to therapy, which is in line with our previous report of a high AFP expression in HC-AFW1-cells." (PMID 26515460, 2015). "Serum AFP is a well-known diagnostic biomarker for HCC, as well as a useful prognostic indicator for HCC patients at the time of tumor diagnosis." (PMID 25633810, 2015). "Our previous study evaluated the sensitivities of tumor markers, including CEA, PSA and AFP, and demonstrated that the tumor markers were abnormally elevated in 73% of SMUP patients." (PMID 26115010, 2015). "Patients with large tumor size, high AFP level, microvascular invasion and HBeAg positive were more likely to be peritumoral Cbl_lo, whereas, intratumoral Cbl density did not demonstrate any correlation to any clinicopathologic features." (PMID 26474280, 2015).
tumor (continued). "As an early clinical response after 2 weeks of sorafenib therapy, changes in intra-tumor blood flow on contrast-enhanced computed tomography (CE-CT), alpha-fetoprotein (AFP) levels, and remnant liver function were investigated." (PMID 26421430, 2015). "The serum amylase, lipase, and tumor markers including AFP, carbohydrate antigen 19-9 (CA 19-9), and carcinoembryonic antigen (CEA) were all normal." (PMID 25986692, 2015). "The tumour marker alpha fetoprotein was grossly elevated at relapse and the tumour was visible on radiological investigation." (PMID 26428307, 2015). "Their pre-operative AFP levels were 1890, 784 and 224 μg/l, respectively, and returned to normal levels (0–20 μg/l) within four weeks of the surgical removal of the tumor." (PMID 25624892, 2015). "The decrease of AFP levels in tumor bearing mice is promising for the use of additive micellar curcumin in the treatment of children with HCC." (PMID 26515460, 2015). "miR-1236 was down-regulated in HCC tissues relative to adjacent non-tumor tissues, while AFP was up-regulated in HCC tissues." (PMID 25714026, 2015). "Serum tumor markers were normal except lactate dehydrogenase (LDH): alpha-fetoprotein (AFP) 5,2 μg/L (≤7), human chorionic gonadotrophin (HCG) 2,9 UI/L (≤5), and LDH 440 UI/L (1,8 N)." (PMID 26000192, 2015). "For comparison, AFP values of different tumor size or differentiation status or liver function were also analyzed." (PMID 25871387, 2015). "But we can exclude the possibility that miR-224 merely reflects liver damage, because significant relation is also evident between miR-224 and serum AFP, which indicates that it also can reflect the status of tumor." (PMID 25688365, 2015). "The tumor marker, alpha-fetoprotein (AFP), is detected in approximately 39–65 % of HCC patients, and has been used as a diagnostic tool." (PMID 26681337, 2015). "To further examine the relationship between IBL and recurrence-free survival, we performed stratified analysis according to the Milan criteria, status of vascular invasion, AFP levels, and tumor differentiation." (PMID 26472203, 2015). "Univariate analysis showed that HBsAg, serum AFP level, tumor size, tumor number, vascular invasion, TNM stage, and ITPKA expression were prognostic factors for OS and RFS." (PMID 26249031, 2015). "Patients were stratified by serum AFP level, presence of tumor vascular invasion, Child-Pugh grade, and cellular differentiation to measure their association with OS and PFS." (PMID 26449224, 2015). "Serum levels of tumor markers, including AFP, carcinoembryonic antigen (CEA) and carbohydrate antigen (CA)-199 were out of the normal range." (PMID 25624892, 2015). "The disappearance of PVTT in the current AFP-GC by chemotherapy with S-1 plus cisplatin conferred operability on this case, resulting a long-term tumor-free survival after the curative operation." (PMID 25591731, 2015). "Tumor markers were almost in a normal range, but one patient showed a high alpha-fetoprotein (AFP) level of 11.5 ng/ml (reference range <7 ng/ml) before hepatic resection." (PMID 26366342, 2015). "Current diagnostic methods such as imaging techniques and serological tumor markers, alpha-fetoprotein (AFP), Lens culinaris agglutinin-reactive AFP, and des-γ-carboxy prothrombin are insufficient for early detection of HCC." (PMID 26352740, 2015). "Eight months after initiation of sorafenib, his AFP level was decreased to normal level, and both the tumor thrombi in the right portal vein and multiple lung metastases disappeared on CT imaging." (PMID 25889667, 2015). "The tumor marker alpha-fetoprotein (AFP) is secreted in 39–65% of HCC patients, and has been used as a diagnostic tool." (PMID 26252472, 2015). "Elevated levels of AFP or DCP were associated with malignant potential such as vascular invasion, tumor differentiation, and intrahepatic metastases, but they have different relationships with a number of clinicopathological variables of HCC." (PMID 25992784, 2015).
tumor (continued). "HBV infection caused malignant transformation of liver, during this course, AFP gene was activated in liver cells, so AFP was used as a tumor marker for early warning origination of HCC in clinical diagnosis." (PMID 25943101, 2015). "Alpha fetoprotein(AFP) is an early biomarker of HCC diagnosis, promote tumor cells proliferation effects of AFP have been reported by several groups, furthermore, data indicated that AFP play pivotal role in the hepatocarcinogenesis." (PMID 25943101, 2015). "The HAP score is a simple scoring index requiring the measurement of two tumor variables (alpha-fetoprotein and the largest size of tumor) and two liver variables (albumin and bilirubin) and can predict outcomes in transcatheter arterial embolization/TACE." (PMID 25919025, 2015). "In conclusion, the utility of DCP for the diagnosis of HCC among Nigerian patients was higher than that of AFP for large tumours with diameter ≥3 cm." (PMID 26341083, 2015). "Serum AFP levels were found to be significantly correlated with larger tumor size in this study (r = 0.36; P = 0.022)." (PMID 25737783, 2015). "We also reported that AFP was able to block RA-RAR signaling to promote tumor cell growth and interrupt the onward transduction of apoptotic signaling by binding with caspase-3." (PMID 25815363, 2015). "Testicular tumor markers were elevated, with an alpha-fetoprotein (AFP) level of 9.3 ng/mL and a beta-hCG level of 3.1 mIU/mL." (PMID 25705541, 2015). "Non- delineation of tumour sizes led to the discrepancies in earlier reports on the sensitivity and specificity of AFP and DCP." (PMID 26341083, 2015). "Serological markers are most commonly used clinically, whereas among the conventional tumor markers, serum alpha-fetoprotein (AFP) is not only used for diagnosis, but also as a prognostic indicator for HCC patients." (PMID 26097877, 2015). "Patients with high AFP levels at the time of diagnosis tended to have greater tumor size, bilobar involvement, massive or diffuse types and portal vein thrombosis." (PMID 26097877, 2015). "Based on multivariate analysis of the entire cohort, independent factors for OS were tumor size, tumor capsule, pathological grades, total bilirubin, albumin, prothrombin time, alpha-fetoprotein, and tumor number, which were incorporated into the nomogram." (PMID 25776856, 2015). "Here, we present the first case of pure AFP-producing pNET, in which the AFP-producing site was immunohistochemically confirmed in the tumor tissues." (PMID 25886790, 2015). "Serial AFP examinations are useful for diagnosis, determination of the completeness of malignant tumor removal, tumor recurrence during the follow-up period, and formation of the prognosis." (PMID 26504900, 2015). "Child-Pugh Class, tumor size, extent of PVI and type of ES, AFP level were independent factors associated with survival." (PMID 25923439, 2015). "Since 1970 s, AFP has been used as the most important tumor biomarker for HCC diagnosis in clinically." (PMID 26497223, 2015). "ECOG performance status, concurrent VI and Mets, tumor size, serum AFP, bilirubin, creatinine, albumin, and AST levels were baseline factors associated with OS." (PMID 25860213, 2015). "In the overall cohort of 777 patients with HCC, LRG1, along with tumor size, tumor multiplicity, serum level of AFP, tumor differentiation, vascular invasion and TNM, were identified as independent prognostic factors." (PMID 26517349, 2015). "These were higher than AFP sensitivity of 78 % for tumour size > 5 cm and 68 % for tumour size 3-5 cm at a cut-off point of 20 ng/ml." (PMID 26341083, 2015). "Traditional clinicopathological parameters such as imaging parameters, serum alpha fetoprotein level and tumor stage only offer limited efficacy for prognosis prediction and fail to effectively guide the individualized therapeutics for HCC2." (PMID 25826294, 2015).
tumor (continued). "AFP, which is a HCC marker often associated with tumor size, was also significantly high in HBV-HCC patients than non-HBVHCC patients." (PMID 25767469, 2015). "Next, tumor-related factors (DCP, AFP, AFP-L3, tumor size, tumor number, vascular invasion, TNM stage, and therapeutic method) were compared between the NBNC-HCC and the B/C-HCC patients according to the status of the semiannual and nonsemiannual surveillance." (PMID 26494948, 2015). "Correlation regression analysis showed that high expression of CCAT1 was significantly correlated with tumor size (p = 0.013), microvascular invasion (p = 0.032), and AFP (p = 0.011)." (PMID 25884472, 2015). "Univariate analysis revealed that tumor differentiation (P = 0.002), clinical N classification (P = 0.01), AFP (P = 0.001) and administration approach to NAC (P = 0.016) were significantly associated with pathological response." (PMID 26620627, 2015). "After adjusting for other confounding factors, high expression of FAM83D, AFP ≥100 ng/ml, median tumor size ≥5 cm and AST ≥40U/l were also identified as independent prognostic factors for the DFS and OS by the multivariate analysis in this study." (PMID 26125229, 2015). "Multivariate analysis revealed that the factors associated with mortality were serum albumin ≤3.5 g/dL (hazard ratio [HR] 1.459), alpha-fetoprotein >20 ng/mL (HR 1.863), tumor size >3 cm (HR 1.542), BCLC stage A2–A4 (HR 1.488), and treatment modality." (PMID 26512620, 2015). "Our early experience of sorafenib therapy also showed a good anti-tumor effect and prognosis in patients whose tumor staining had disappeared on CE-CT and whose AFP level had decreased in the early post-dose period (i.e., the first 2 weeks post-dose)." (PMID 26421430, 2015). "Some reports suggest that early AFP response after sorafenib therapy is a useful surrogate marker for anti-tumor response and outcomes." (PMID 26421430, 2015). "This was effective in reducing the residual tumor and lung metastases, but tumor thrombi appeared in the right portal vein, and his AFP and PIVKA-II levels were elevated to 41,948 ng/ml and 422 mAU/mL, respectively." (PMID 25889667, 2015). "In contrast, the present study compared survival and recurrence rates of HR versus LT for HCC between well-matched groups, including Child-Pugh classification, tumor number, tumor size, AFP, and DCP levels." (PMID 25922554, 2015). "We established a preoperative prognostic score model by calculating the number of independent predictors (FAM83D, AFP, tumor size, and AST) for each patient." (PMID 26125229, 2015). "We also found that tumor characteristics, including serum AFP levels, either macro- or microvascular invasion, and the Milan criteria, were significant independent predictors of HCC recurrence after LT, which is consistent with previous reports." (PMID 26472203, 2015). "Of the 11 cases, 6 cases died of the primary AFP-producing tumor and 2 cases died of postoperative complications." (PMID 25962419, 2015). "We evaluate relationships between treatment modality (HR, TACE, and RFA) and survival in HCC patients, according to pre-treatment and 3-month post-treatment serum AFP levels and pre-treatment tumor diameter." (PMID 24993566, 2014). "The tumor markers alpha-fetoprotein and beta-HCG were within normalcy range and lactate dehydrogenase was raised." (PMID 24728256, 2014). "A study of 12,118 HCC patients found that tumor diameter and serum AFP levels were predictive for patients who underwent HR, with tumors measuring < 20 mm in diameter having better prognoses than tumors measuring 20–50 mm in diameter." (PMID 24993566, 2014). "Univariate Cox regression analyses revealed that higher levels of PHD2, tumor size, tumor stage, as well as serum AFP levels were all worse predictors for HCC prognosis." (PMID 25546659, 2014). "And a high AFP level, more tumor number, and an advanced TNM staging of HCC were more detected in those patients with low 5-hmC expression in validation cohort." (PMID 24716838, 2014).